TNF (tumor necrosis factor)
Diseases named in the same sentence as TNF in open-access papers (continued):
Sharing a sentence is not in itself a finding about the gene and the disease.
leishmaniasis (continued). "TNF-α constitutes a clear risk factor for disease development and immunotherapies directed to its production, such as TNF-α blockers, have been proposed as a treatment against leishmaniasis." (PMID 35456085, 2022). "Patients with recurrent leishmaniasis presented a positive correlation between the levels of IL-2, IL-4 and TNF (p<0.001)." (PMID 36017367, 2022). "This study showed that in response to L. infantum, human peripheral blood MAIT cells from children with leishmaniasis produced TNF and IFN-γ in an MR1-dependent manner." (PMID 36189274, 2022). "Additional epidemiology comes from studies of at-risk populations in Italy and Spain looking at the prevalence of positive leishmaniasis testing in patients on TNF-α inhibitor therapy." (PMID 33799892, 2021). "The inflammatory cytokines such as interferon-γ, IL-1beta, IL-6, IL-8, and TNF-α are involved with leishmaniasis severity." (PMID 34735436, 2021). "LdPP2C affects the host innate immune response by upregulating pro-inflammatory cytokines (TNF-α and IL-6) as well as nitric oxide, while LcPP2C elicits a strong proliferative response of T cells in patients with leishmaniasis." (PMID 33937094, 2021). "Asiaticoside has been shown to have immunomodulatory properties against Leishmaniasis where it induced TNF-α production in peritoneal macrophages." (PMID 34367513, 2021). "TNF-α has pro-inflammatory effects but also plays an important role in the defense against intracellular infections, such as leishmaniasis." (PMID 31463070, 2019). "Once the leishmaniasis is confirmed, systemic drug treatment and the discontinuation of the TNF-α blockers therapy until clinical recovery seems to be the best therapeutic approach when possible." (PMID 31469834, 2019). "We performed a retrospective observational study including patients with confirmed leishmaniasis acquired in the Mediterranean basin that were under TNF-α blockers therapy at the moment of the diagnosis." (PMID 31469834, 2019). "The patients with TNFα modulating therapy infected with leishmaniasis while visiting a treatment clinic in Spain enlightens the importance of increased suspicion of leishmaniasis and further studies in this group of patients." (PMID 29848389, 2018). "The anti-TNF-α action of pentoxifylline makes its use interesting, mainly in cases of mucosal and/or treatment-refractory leishmaniasis, since this cytokine is the main responsible for mucosal damage." (PMID 30675152, 2018). "Taken together, we provide an in vitro model of human leishmaniasis that allows direct comparison of different anti-TNFα agents." (PMID 30108591, 2018). "The higher production of TNF-α and IL-6 after TLR4a blood stimulation when compared to untreated blood is in agreement with several studies carried out in murine and human leishmaniasis where TLR4 regulated the initial proinflammatory response." (PMID 30539014, 2018). "Our results enhance the understanding of the efficacy and adverse effects of TNFα blockers and they contribute to evaluate anti-TNFα therapy for patients living in countries with a high prevalence of leishmaniasis." (PMID 30108591, 2018). "A protective immune response against leishmaniasis has been associated with an efficient cell response resulting in the production of cytokines such as IL-12, IFN-gamma, and TNF-alpha that leads to activation of macrophages and parasite elimination." (PMID 29358935, 2017). "Secretion of IL-12, IL-2, IFN-γ and TNF-α as cytokines released after activation of T helper 1 protects human against leishmaniasis." (PMID 28979355, 2017). "NK cells are among the first to produce IFN-γ and TNF-α in response to pathogen presence and in leishmaniasis, these cells can become activated after the binding of TLR2 to Leishmania LPG." (PMID 27031998, 2016). "In previous experiments, we observed a fatal visceral form of leishmaniasis in L. major-infected C57BL/6 TNF-/- mice." (PMID 26834705, 2015).
leishmaniasis (continued). "Recently, the balance between pro-inflammatory IFN-γ/TNF-α and regulatory IL-10 cytokines has been shown to be involved in the outcome of human leishmaniasis and in the prediction of vaccine success." (PMID 24786587, 2014). "Apart from IFN-γ, tumor necrosis factor (TNF) has also been shown to play important role in protective immunity against leishmaniasis." (PMID 23776605, 2013). "Even an excess production of TNF often proved to be detrimental in cerebral malaria, erythema nodosum leprosum and leishmaniasis." (PMID 22276993, 2012). "It has been also demonstrated that CD4+ T cells that expresses IFNγ and TNFα play an important role in therapy against leishmaniasis." (PMID 22715418, 2012). "We report 2 new cases of leishmaniasis involving patients with autoimmune rheumaticdiseases who received anti–tumor necrosis factor (anti-TNF) agents." (PMID 19523302, 2009). "Our data suggest that the introduction of TNF blockade into the clinical practice isassociated with increasing reports of leishmaniasis in patients with autoimmunerheumatic diseases who live in leishmaniasis-endemic areas of Europe." (PMID 19523302, 2009). "Prospective studies to estimate the incidence of the disease, the impact of riskfactors and the need for serologic screening for leishmaniasis before initiation ofanti-TNF agents or any other immunosuppressive treatment are clearly needed." (PMID 19523302, 2009). "IFN-γ and TNF-α are important cytokines for the outcome of infection in the experimental models of leishmaniasis." (PMID 16638143, 2006). "Hence, immunosuppressive drugs, especially tumor necrosis factor (TNF) inhibitors, can favor the development of clinically evident leishmaniasis as well as relapses after appropriate treatment." (PMID 41148639, 2025). "Moreover, in previous studies, IP-10, and IFN-γ levels proved useful in monitoring the cellular immune response following treatment for active disease and IFN-γ, TNF-α, IL-10 and IL-2 indicated exposure to leishmaniasis." (PMID 40142579, 2025). "TNF, IFN-γ, and IL-17A have been strongly associated with protection during leishmaniasis." (PMID 36189274, 2022). "KEGG pathway analysis revealed the involvement of these genes mainly in the IL−17 signaling pathway, epithelial cell signaling in Helicobacter pylori infection, Leishmaniasis, C−type lectin receptor signaling pathway, and tumor necrosis factor signaling pathway." (PMID 36329882, 2022). "It is well known that pro-inflammatory (e.g., IFN-γ, TNF-α, IL-1, IL-12) and anti-inflammatory (e.g., IL-4, IL-10, TGF-β) cytokines play different roles in resistance/susceptibility and the immunopathogenesis of leishmaniasis." (PMID 33114674, 2020). "Indeed, it is known that several Swedish patients undergoing tumor necrosis factor (TNF)-α modulating therapy became infected with leishmaniasis while visiting Spain." (PMID 31164191, 2019). "Inhibition or lack of TNF-α activity seem to induce an increased risk of leishmaniasis as demonstrated in mouse models." (PMID 31463070, 2019). "and the emergence of clinical signs of leishmaniasis–thus confirming the protective role of TNF-α+." (PMID 29543867, 2018). "Based on our results, we propose that anti-TNFα therapy using Cimzia® may be advantageous for patients living in high-incidence areas of leishmaniasis." (PMID 30108591, 2018). "Leishmania recognition by monocytes or macrophages through TLRs leads to the production of proinflammatory cytokines such as tumor necrosis factor (TNFα), interleukin (IL)-6, and interferon gamma (IFNγ), which all contribute for the exacerbated inflammation in leishmaniasis lesions." (PMID 29123157, 2017). "Fourth, in our present study we showed that mice deficient for TNF or TNFR1 overexpressed IFN-γ and displayed intact, relatively strong expression of iNOS in the draining LN, yet, counterintuitively, developed progressive, and ultimately fatal leishmaniasis." (PMID 26834705, 2015).
leishmaniasis (continued). "TNF-α has a potent function against mouse model of leishmaniasis." (PMID 26622301, 2015). "Leishmania-induced IL-12 and TNF-α in matured DCs, was associated with the capacity of these cells to induce Th1 responses and IFN-γ production which are critical for resistance and cure of leishmaniasis." (PMID 26581100, 2015). "Similar to pentoxifylline, Dolabelladienetriol could be an important tool for leishmaniasis control that occurs with high TNF-α levels through its capacity to inhibit this cytokine." (PMID 22970332, 2012). "TNF-α plays an important role in protecting humans and mice against leishmaniasis." (PMID 22458474, 2012). "Moreover, the clinical improvement of leishmaniasis patients treated with pentoxifylline, a TNF-α inhibitor, has been shown." (PMID 22970332, 2012). "Moreover, dipeptidyl peptidase-4 (Dpp4) upregulation also exacerbates the reduced capacity of anti-TNF immunosuppressed mice to eliminate the infection, as its increased presence has been observed in unresolved cases of leishmaniasis compared to levels in cured patients and controls." (PMID 40808943, 2025). "Thus, TNF- α levels are crucial for the outcome of leishmaniasis and could be of interest to investigate the impact of anti-leishmania drugs on this pro-inflammatory cytokine." (PMID 35456085, 2022). "Mice lacking TNF are highly susceptible to both cutaneous and visceral leishmaniasis." (PMID 32948646, 2020). "However, to our knowledge, it has not been investigated whether retrograde axonal transport of TNF-α and its receptors occurs in leishmaniasis." (PMID 31138231, 2019). "Finally, with the results extracted from this study it is not possible to assess the risk of developing clinical leishmaniasis during anti TNF-α therapy." (PMID 31469834, 2019). "Importantly, while TNF is induced in LPS-stimulated Ahr knockout macrophages, production of NO is inhibited, indicating an ambiguous nature of AhR-signaling in terms of macrophage functions relevant for Leishmaniasis." (PMID 31749794, 2019). "A balance between the proinflammatory response characterized by the production of IFN-γ and TNF, and the regulatory response with the production of IL-10 has been observed in individuals exposed to the Leishmania braziliensis in endemic areas of leishmaniasis in Brazil." (PMID 23209879, 2012). "In mononuclear cells from dogs with leishmaniasis, the cytokines rcaIL‐12/rcasIL‐10R1 induced IFN‐γ and TNF‐α production in PBMCs." (PMID 40799008, 2025). "The clinical cure or resistance to leishmaniasis contributes to Th1 propagation and the production of pro-inflammatory cytokines, including IL12p40, IFN-γ, and TNF-α, which leads to macrophage proliferation and eventual parasite death." (PMID 39213335, 2024). "No changes were observed in the production of IL-6, TNF-α, or IFN-y in the PBMC culture supernatants of healthy dogs and those with leishmaniasis after transfection with miR-194 Mimic and Inhibitor." (PMID 38241360, 2024). "Regarding the pro-inflammatory cytokines IL-1β, IL-6, TNF-α, and IFN-y, only IL-1β increased in PBMC culture supernatants from dogs with leishmaniasis after transfection with the miR-194 inhibitor." (PMID 38241360, 2024). "Test for a possible regulatory role of miR-194 in the production of cytokines IL-1β, IL-6, IL-4, TNF-α, IFN-y, TGF-β, and IL-10, PBMCs from healthy dogs and those with leishmaniasis were transfected with miR-194 Mimic and Inhibitor." (PMID 38241360, 2024). "In leishmaniasis, the activation of macrophages by IFN-γ induces the production of IL-12, TNF, reactive oxygen species (ROS), and nitric oxide (NO) to eliminate the parasite." (PMID 38143766, 2023). "In the murine model of leishmaniasis, TLR4 is required for efficient parasite control and in vitro studies demonstrated that GP29, a L. donovani derived glycoprotein, induced TNF-α and IL-12 production through TLR4 activation." (PMID 34832536, 2021).
leishmaniasis (continued). "In Tegumentary Leishmaniasis the subclinical infection is characterised by a lower IFN-g and TNF-a production, suggesting that this modulated immune response has the ability to control infection without causing pathology." (PMID 32321156, 2020). "Leishmaniasis induced significant increase of spinal cord GFAP, Iba-1, TNF-α, IL-1β, CX3CR1, and CX3CL1 mRNA expression, which were inhibited by α-aminoadipate, minocycline, and PDTC treatments (p < 0.05)." (PMID 31138231, 2019). "In this report, we want to highlight the importance of awareness of leishmaniasis as a possible and potentially very severe infection in patients treated with anti-CD20 and with anti-TNF-α after travel to endemic regions." (PMID 31431985, 2018). "The degree of protection against various infections including leishmaniasis is predicted by the frequency of polyfunctional CD4+ memory T cells that produce IFN-γ, TNF-α, and IL-2." (PMID 26485398, 2015). "Activation of NK cells by leishmaniasis results in secretion of cytokines such as interferon (IFN)-γ and tumor necrosis factor (TNF)-α, which enhance the phagocytosis and clearance of parasite." (PMID 26622301, 2015). "For example, IFN-γ/TNF-α and RNS production can be detected during chronic human leishmaniasis, and the development of drug resistance in Leishmania is closely linked to the redox biology of the parasite." (PMID 25033301, 2014). "In experimental leishmaniasis, the activation of macrophage and production of Th1 cytokines, IFN-γ and TNF-α, are required to eliminate Leishmania parasite." (PMID 24267152, 2013). "It clearly shows that an efficient vaccine against leishmaniasis should not only induce IFN-γ-, TNF- and IL-2-secreting memory T cells, but also needs to prevent the development of antigen-specific IL-10-secreting T cells." (PMID 23825956, 2013). "In leishmaniasis, cytokines such as interferon-gamma (IFN-γ) and tumor necrosis factor alpha (TNF-α) have a major role in controlling intracellular growth of the etiological pathogen." (PMID 17456233, 2007). "The identification of hub genes of recruited datasets suggested that TNF, SOCS3, JUN, TNFAIP3, and CXCL9 may serve as potential infection biomarkers and could deserve value as prognostic biomarkers for leishmaniasis." (PMID 38839916, 2024). "TNF-α, IFN-λ, and other proinflammatory cytokines may influence the outcome of leishmaniasis because they play an important role in macrophage activation and activate inducible nitric oxide synthase." (PMID 37319132, 2023). "Furthermore, KEGG enrichment analysis revealed the following pathways (p < 0.05): NF-kappa B, C-type lectin, TNF, MAPK, IL-17, toll-like receptor, and T cell receptor signaling pathways and leishmaniasis." (PMID 34987704, 2021). "Interestingly, dogs with leishmaniasis also showed a significant increase in IFN-γ and TNF-α production by PBMCs cultured with rcaIL-12/rcaIL-2 or rcaIL-12/rcaIL-15 combinations with or without the addition of SLA." (PMID 31961868, 2020). "It is worth noting that high NO production is considered fundamental for the resolution of leishmaniasis; however, NO production is not completely dependent on TNF-α secretion." (PMID 31882925, 2019). "We demonstrate the relevance of sTNFα for parasite control in human leishmaniasis and the negative impact of various anti-TNFα agents as treatment with Remicade®, Remsima®, and Humira® increased infection rates in human macrophages." (PMID 30108591, 2018). "The significant recognition of LACK by the T receptors of the present cured and asymptomatic subjects, plus the ability of this protein to induce IFN-γ, TNF-α, and granzyme B (CD4+ and CD8+ T cell responses), indicates this antigen to be of potential use in vaccines against human leishmaniasis." (PMID 29740446, 2018).
leishmaniasis (continued). "The production of IFN-γ, TNF-α, granzyme B, IL-5 and IL-10 by SLA-stimulated PBMCs, and of IFN-γ, TNF-α and IL-2 by SLA-stimulated whole blood, could be used to indicate exposure to leishmaniasis, especially for patients subjected to induced immunosuppression." (PMID 26496365, 2015). "Leishmaniasis associated cytokine profiles (interferon-gamma (IFN-γ) and tumor necrosis factor-alpha (TNF-α among others) were not analyzed." (PMID 26541197, 2015). "T cells that produce multiple factors simultaneously (e.g. TNF-α, IL-2 and IFN-γ) are termed polyfunctional T cells and have been shown to provide protection against diseases in murine models of Leishmaniasis and TB, control of hepatitis C and HIV-1 infection and possibly vaccine-induced immunity." (PMID 24959834, 2014). "IL-27 was not able to suppress TNF-α production by cells from leishmaniasis patients: In addition to its role in stimulating a Th1-type immune response, IL-27 is known to attenuate inflammatory cytokine production." (PMID 24485388, 2014). "We cannot also exclude the possibility that the concomitant,long-term use of other immunosuppressants, and not the anti-TNF agents per se,played a crucial role in the development of leishmaniasis." (PMID 19523302, 2009). "Importantly, a novel tumor necrosis factor (TNF)-and inducible nitric oxide synthase (iNOS)-producing DCs (TIP-DCs) subset has been reported to exert a pivotal role in the course of several infectious diseases, including experimental leishmaniasis." (PMID 30873156, 2019). "Twenty-five (51%) patients were under infliximab treatment at the moment of leishmaniasis diagnosis, twenty (40.8%) were receiving adalimumab, two (4.1%) were receiving etanercept, one (2%) golimumab and another one (2%) received a non-specified TNF-α blocker." (PMID 31469834, 2019). "Besides, the chemokine MIP-1α (CCL3) is known to induce IL-1, IL-6, and TNF-α production with chemotactic and pro-inflammatory effects and acts as homeostasis promoter culminating in a Th1 response in the presence of receptors CCL3 and CCR5, fundamental in the control of leishmaniasis." (PMID 34253188, 2021).